TEX51 (testis expressed 51)
Gene: Protein-coding gene on chromosome 2 (126,898,864 to 126,902,097, forward strand). Ensembl gene ENSG00000237524.
Subcellular location: Membrane
Gene Ontology:
Cellular component: membrane
Homologues: Orthologues: chimpanzee TEX51 (92% identical), macaque TEX51 (89% identical), mouse Tex51 (56% identical), rat Tex51 (55% identical).
Diseases named in the same sentence as TEX51 in open-access papers:
TEX51 is named in the same sentence as 2 diseases in open-access papers, as found by Europe PMC text mining. Sharing a sentence is not in itself a finding about the gene and the disease.
TEX51 shares sentences with these, for which no sentence is quoted: neuroendocrine disorder (1 paper); Obesity (1).